Y_RNA (Y RNA )
Gene: Miscellaneous RNA gene on chromosome 21 (17,576,798 to 17,576,906, forward strand). Ensembl gene ENSG00000199962.
Homologues: Orthologues: chimpanzee Y_RNA (97% identical), macaque Y_RNA (85% identical). Paralogues in human: RNY1 (83% identical), Y_RNA (83% identical), Y_RNA (82% identical), Y_RNA (81% identical), RNY1P11 (80% identical), Y_RNA (80% identical), Y_RNA (79% identical), Y_RNA (78% identical), RNY1P12 (77% identical), RNY1P15 (77% identical), Y_RNA (77% identical), RNY1P8 (76% identical), and 93 more.